NR2F6 (nuclear receptor subfamily 2 group F member 6)
Diseases named in the same sentence as NR2F6 in open-access papers (continued):
Sharing a sentence is not in itself a finding about the gene and the disease.
endometrial carcinoma (1 paper, 2023). A malignant tumor arising from the epithelium that lines the cavity of the uterine body. "The survival analyses in this study show that an NR2F6 overexpression is associated to a better disease-free and overall survival in endometrial cancer patients, respectively." (PMID 36884115, 2023). "In the future, the impact of NR2F6 on chemosensitivity and on immune checkpoint therapy as well as the role of NR2F6 on effector T cells in endometrial carcinomas should be elucidated." (PMID 36884115, 2023). "These are new insights into survival analyses revealing the prognostic impact of NR2F6 across the most common molecular subgroups in endometrial cancer patients." (PMID 36884115, 2023). "This is the first study investigating the role of the orphan nuclear receptor NR2F6 in endometrial cancer tissue." (PMID 36884115, 2023). "Expression analysis of NR2F6 in 142 endometrial cancer patients was performed by immunohistochemistry of primary paraffin‐embedded tumor samples." (PMID 36884115, 2023). "The results suggest that NR2F6 may play an important role in the cell cycle and carcinogenesis of endometrial cancers." (PMID 36884115, 2023). "In this study, we could demonstrate that there is a longer progression-free and overall survival for NR2F6-positive patients with endometrial cancer." (PMID 36884115, 2023). "The prognostic impact of NR2F6 in endometrial cancers is evaluated in this study." (PMID 36884115, 2023). "We conclude that NR2F6 might play a crucial role in endometrial cancer growth and cell differentiation." (PMID 36884115, 2023). "Our results suggest, that NR2F6 may influence independently from molecular subgroups the prognosis of endometrial cancer patients." (PMID 36884115, 2023). "We conclude that NR2F6 might play an essential role in endometrial cancers." (PMID 36884115, 2023).
glioblastoma (1 paper, 2015). The most malignant astrocytic tumor (WHO grade IV). "Two mRNAs whose expression characterizes LTCs vs LTPs, LRFN3 (encoding for Leucine Rich repeat and Fibronectin type III domain containing 3) and NR2F6 (Nuclear Receptor subfamily 2 group F member 6), were previously included in the “classical” signature of glioblastoma." (PMID 26188123, 2015).
hepatoblastoma (1 paper, 2021). Hepatoblastoma (HB) is a malignant hepatic tumor and is the most common pediatric liver cancer. "After the evaluation of NR2F6 expression, the potential diagnostic effectiveness of increased NR2F6 level in hepatoblastoma was further explored with nine included studies." (PMID 34304715, 2021). "We are the first to confirm the overexpression of NR2F6 in hepatoblastoma tissues, utilizing large-sample evaluation from multi-region and multi-source samples." (PMID 34304715, 2021). "In the current study, overexpressed NR2F6 in hepatoblastoma tissues was confirmed through 440 samples." (PMID 34304715, 2021). "Odds ratio (OR) forest plot also suggested that the population with upregulated NR2F6 levels was more likely to suffer from hepatoblastoma (OR = 25.1; 95% CI:10.45, 60.26)." (PMID 34304715, 2021). "Accordingly, targeting NR2F6 holds a therapeutic promise in treating residual recurrent hepatoblastoma after incomplete ablation." (PMID 34304715, 2021). "According to GO analysis, the genes targeted by NR2F6 in residual hepatoblastoma were clearly involved in the processes of basement membrane organization, reverse cholesterol transport, and high-density lipoprotein particle remodeling (biological process)." (PMID 34304715, 2021). "Meanwhile, NR2F6 protein was found to interact with 2,233 target genes in hepatoblastoma HepG2 cells from 4 ChIP-seq studies." (PMID 34304715, 2021). "Therefore, we mainly focused on and mainly discussed the lipid metabolic regulation of NR2F6 in residual hepatoblastoma." (PMID 34304715, 2021). "Besides, although increased levels of NR2F6 mRNA were detected in both hepatoblastoma and residual tumor, changes of NR2F6 protein should be further validated by Western blot or immunochemistry." (PMID 34304715, 2021). "In addition, the targets of NR2F6 in residual hepatoblastoma were significantly related to the regulation of lipid metabolism as indicated by GO annotation and pathway analysis." (PMID 34304715, 2021). "Nevertheless, whether NR2F6 is a direct factor to incite more progression of residual hepatoblastoma justifies further investigation." (PMID 34304715, 2021). "We therefore hypothesized that overexpressed NR2F6 might contribute to the carcinogenesis of hepatoblastoma." (PMID 34304715, 2021). "Interestingly, nude mouse xenografts provided direct evidence that overexpressed NR2F6 was also detected in residual tumor compared to untreated hepatoblastoma." (PMID 34304715, 2021). "Based on the ROC curves for each dataset, the results (AUC> 0.7) of eight studies indicated that NR2F6 had a relatively high ability to differentiate between hepatoblastoma and non-cancer child livers." (PMID 34304715, 2021). "The overexpression of NR2F6 also appeared to be an efficient indicator in distinguishing hepatoblastoma tissues from non-cancer liver tissues from the indication of a summarized AUC of 0.90, with a pooled sensitivity of 0.76 and a pooled specificity of 0.89." (PMID 34304715, 2021). "In this study, we confirmed a higher expression of NR2F6 in 219 cases of hepatoblastoma than 121 cases of non-cancer child liver by combining high throughput RNA sequencing (RNA-seq) data." (PMID 34304715, 2021). "In seven datasets among nine studies, NR2F6 exhibited clearly higher levels in hepatoblastoma tissues than non-cancer child livers (p < 0.05)." (PMID 34304715, 2021). "In the current research, a higher NR2F6 expression was confirmed in hepatoblastoma than non-cancer liver with a combination of RNA-seq and microarrays samples, including 219 hepatoblastoma tissues and 121 non-cancer liver tissues (SMD = 1.04; 95% CI: 0.79, 1.29)." (PMID 34304715, 2021). "In this study, we integrated 219 hepatoblastoma and 121 non-cancer liver tissues to evaluate the expression of NR2F6, from which a higher NR2F6 level was found in hepatoblastoma compared with non-cancer livers with a standard mean difference (SMD) of 1.04 (95% CI: 0.79, 1.29)." (PMID 34304715, 2021).
hepatoblastoma (continued). "Besides, the overall AUC of 0.9 further revealed that overexpressed NR2F6 might act as a potential biomarker to distinguish hepatoblastoma and non-cancer liver tissues with a sensitivity of 0.76 and a specificity of 0.89, suggested by the summarized ROC integrated by 440 samples." (PMID 34304715, 2021).
malaria (1 paper, 2025). Malaria is a serious and sometimes fatal disease caused by a parasite that commonly infects a certain type of mosquito which feeds on humans. "To determine whether NR2F6 could modulate malaria pathogenesis, we first infected wild-type and whole-body Nr2f6-knock-out mice with Plasmodium berghei ANKA (PbA) parasites (7.5 × 104 parasitized red blood cells, pRBC)." (PMID 40801595, 2025). "This indicates that NR2F6 loss protects mice from ECM but not from malaria-induced hyperparasitemia and death." (PMID 40801595, 2025). "While the direct link between NR2F6 and immune effector cell trafficking to the brain remains to be fully elucidated, these findings highlight the potential of NR2F6 as a molecular regulator of immunopathology during severe malaria." (PMID 40801595, 2025). "As we observed a trend of lower parasitemia in Nr2f6-knock-out mice, one could speculate that this results in less pathology, with the observed protection potentially due to enhanced overall resistance to malaria." (PMID 40801595, 2025).
osteosarcoma (1 paper, 2022). A usually aggressive malignant bone-forming mesenchymal neoplasm, predominantly affecting adolescents and young adults. "Based on our analysis, we found that several NRs including NR4A2, NR4A1, NR3C1, NR2F6, and NR2F2 were differentially expressed in osteoblastic cells among metastasis, primary, and recurrent osteosarcomas." (PMID 35965537, 2022).
parasitemia (1 paper, 2025). "Comparable to the clinical score and parasitemia, the progression of temperature loss was analogous in Nr2f6-knock-out mice, showing less temperature loss early after infection." (PMID 40801595, 2025).
periodontitis (1 paper, 2025). An acute or chronic inflammatory process that affects the tissues that surround and support the teeth. "Furthermore, comparison of TF deviation scores in LSK cells from periodontitis and control mice revealed that periodontitis may facilitate neutropoiesis by increasing the accessibility of Rarg and Nr2f6." (PMID 40521205, 2025).
Salmonella Infections (1 paper, 2025). Infections with bacteria of the genus SALMONELLA. "Despite unchanged basal iron metabolism in the spleen and liver, iron regulatory proteins and the interleukin (IL)-6-hepcidin axis are altered in Nr2f6-deficient mice during Salmonella infection, reducing hypoferremia." (PMID 40605423, 2025).
schizophrenia (1 paper, 2013). A major psychotic disorder characterized by abnormalities in the perception or expression of reality. "The identified polymorphisms and the corresponding genes NR2F6, USHBP1 and BABAM1 have not previously been associated with schizophrenia or other neuropsychiatric disorders." (PMID 23805179, 2013). "Elucidating the specific mechanisms of NR2F6, USHBP1 and BABAM1 in the regulation of neurodevelopment and synaptic (re)organization could improve our conceptual framework of processes related to hippocampal volume reduction and facilitate a better understanding of schizophrenia." (PMID 23805179, 2013).
systemic lupus erythematosus (1 paper, 2022). An autoimmune multi-organ disease typically associated with vasculopathy and autoantibody production. "Mice deficient for NR2F6 develop late-onset autoimmunity that resembles systemic lupus erythematosus." (PMID 36052079, 2022).
tumor (42 papers, 2015 to 2025). "In this study, the pancancer analysis of NR2F6 found that NR2F6 appeared as a tumor-promoting factor in various tumor types, and its expression was closely associated with patient prognosis, and higher expression was associated with reduced survival time." (PMID 40424451, 2025). "Tumor-infiltrating NK cell frequencies were similar between genotypes, as were frequencies in the blood and spleens of Nr2f6-deficient mice." (PMID 39920136, 2025). "NKp46 levels were consistently enhanced within Nr2f6-deficient NK cells in the tumor, blood and spleen." (PMID 39920136, 2025). "Of importance, whereas frequencies of terminal mature CD27-CD11b+KLRG1+ NK cells in the spleen were still reduced in Nr2f6-deficient mice, they were rescued to wild-type controls in the blood and the tumor." (PMID 39920136, 2025). "Consistent with tumor growth inhibition seen upon NR2F6 loss, both pathway and upstream regulator analyses of differentially expressed genes (DEGs) identified activation of antitumor immune signaling only in vivo (in bulk tumor and sorted tumor cell samples)." (PMID 37406115, 2023). "To confirm that CD8+ T cell infiltration mediates tumor regression after NR2F6 loss, we depleted CD8+ T cells from mice inoculated with NR2F6-deficient B16F10 cells via injection of anti-CD8 neutralizing antibodies." (PMID 37406115, 2023). "Recent studies have shown that Nr2f6-deficient mice exhibit tumor growth inhibition due to an enhanced anti-tumor immune response against both solid tumors and metastases, leading to overall survival benefit." (PMID 37575237, 2023). "To do so, we engineered NR2F6-deficient B16F10 tumor cells, injected them into immune-competent mice, and collected tumors 12 days later." (PMID 37406115, 2023). "WT mice with NR2F6 depletion in tumor cells showed a 45.85 to 62.95% reduction in tumor growth, while those with systemic NR2F6 loss showed a 30.77% reduction." (PMID 37406115, 2023). "Our previous tumor experiments demonstrated that Nr2f6-deficient mice have superior protective memory responses." (PMID 33589606, 2021). "Along this line of argumentation, genetic deletion of both or even just one allele of the Nr2f6 gene initiates tumor control." (PMID 31937317, 2020). "Especially in combination with the established immune checkpoint therapy of PD-L1 blockade, we observed a host-protective tumor immunity effect in Nr2f6-deficient mice." (PMID 31937317, 2020). "NR2F6 has been identified as an immune checkpoint molecule in tumor-infiltrating T lymphocytes and is associated with a poor prognostic outcome in various cancers." (PMID 32752295, 2020). "We made the remarkable observation that loss of NR2F6 enhances the activity of established PD-L1 checkpoint blockade to promote tumor regression and increased survival in subcutaneous tumor models." (PMID 29670099, 2018). "Several gene signatures known to be favorable for T-cell-mediated tumor rejection were also found to be deregulated in CD3+ TILs from tumor-bearing Nr2f6-deficient mice additionally treated with anti-PD-L1." (PMID 29670099, 2018). "The orphan nuclear receptor NR2F6 (Nuclear Receptor subfamily2group F member 6) is an emerging therapeutic target for cancer immunotherapy.Upregulation of NR2F6 expression in tumor cells has been linked toproliferation and metastasis, while in immune cells NR2F6 inhibitsantitumor T-cell responses." (PMID 40931005, 2025). "Furthermore, when co-cultured with B16 tumor cells, Nr2f6-deficient NK cells exhibited significantly enhanced IFNγ production in percentages and MFI." (PMID 39920136, 2025). "We assume NR2F6 being part of cell signaling pathways which may cause differences of tumor growth in general and, therefore, lead to different survival times." (PMID 36884115, 2023). "Given that tumor-intrinsic NR2F6 loss attenuates B16F10 cell growth, we asked whether ectopic NR2F6 expression would enhance tumor development." (PMID 37406115, 2023).
tumor (continued). "Such a strategy has been suggested by the Baier group who demonstrated the importance of NR2F6 as an intracellular immune checkpoint in effector T cells and later showed that mice genetically deficient in NR2F6 and then inoculated with tumor cells exhibit relatively decreased tumor growth." (PMID 37406115, 2023). "Consequently, the researchers found that NR2F6 expression appears to be associated with quicker tumor progression and worse overall patient survival." (PMID 37575237, 2023). "NR2F6-deficient tumor-bearing mice have enhanced survival via T cell-dependent antitumor immunity." (PMID 34589432, 2021). "Our previous data even indicated that PD-1 is strongly upregulated in Nr2f6-deficient T cells and that a combinatorial blockade of both the PD-L1/PD-1 and the NR2F6 pathways is effective in delaying tumor growth and improving long-term survival with complete tumor regression." (PMID 31937317, 2020). "In order to exclude “emergency” granulo-monocytopoesis as a main or contributing factor to the enhanced tumor rejection in Nr2f6-deficient mice, hematopoietic stem cells, myeloid progenitor cells and myeloid cells within the bone marrow were investigated following tumor induction." (PMID 29670099, 2018). "Thus, not only complete but also partial (50%) NR2F6 deficiency, the latter representing a fairly realistic scenario of therapeutic inhibition, is sufficient to strengthen anti-tumor immunity." (PMID 29670099, 2018). "Of note, the augmented anti-tumor immune response in Nr2f6−/− mice were linked to a markedly higher PD-1 and PD-L1 expression on CD8+ and CD4+ T-cell subsets in vitro when compared to wild-type animals, suggesting a potential resistance mechanism via upregulation of T-cell exhaustion markers." (PMID 29670099, 2018). "Haplo-insufficiency of the Nr2f6 gene function in vivo is shown by the fact that one deficient allele of the Nr2f6 gene was sufficient to increase the immune system’s efficacy to counteract tumor outgrowth." (PMID 29670099, 2018). "Thus, we asked whether antitumor immunity seen following the loss of tumor-intrinsic NR2F6 expression would be augmented in mice genetically deficient in NR2F6." (PMID 37406115, 2023). "Nr2f6-deficient mice show an increased tendency for experimentally-induced neuroinflammation as well as improved intratumoral effector T-cell response resulting in strongly decelerated tumor growth in different spontaneous as well as transplantable mouse tumor models." (PMID 31937317, 2020). "NR2F6 is an orphan nuclear receptor with dual tumorigenic activity in the immune system and tumor cells, playing an essential role in tumor differentiation and immunity." (PMID 40424451, 2025). "Age, COG score, MYCN gene expression, tumor tissue differentiation, and NR2F6 expression were included to construct multifactorial linear regression equations." (PMID 40424451, 2025). "Our study demonstrates that the nuclear orphan receptor NR2F6 represses the expression of the activating receptor NKp46, an established key player in NK cell-mediated cytotoxicity during infection and tumor rejection." (PMID 39920136, 2025). "Given the dual pro-tumorigenic activity of NR2F6 in immune cells and tumor cells, inhibition of NR2F6 expression offers a unique therapeutic potential to improve current treatment outcomes." (PMID 40424451, 2025). "Our immunohistochemistry results aligned with this finding, as poorly differentiated tumor cells exhibited high NR2F6 expression, with a shift from nuclear to cell membrane localization, showing nuclear membrane-positive expression." (PMID 40424451, 2025). "Given the dual tumorigenic activity of NR2F6 in immune cells and tumor cells, inhibition of NR2F6 expression offers a unique therapeutic potential to improve current therapeutic outcomes." (PMID 40424451, 2025). "In our literature search, we discovered that NR2F6 exhibits dual tumor-promoting activities in both the immune system and tumor cells." (PMID 40424451, 2025).